IFNG (interferon gamma)
Diseases named in the same sentence as IFNG in open-access papers (continued):
Sharing a sentence is not in itself a finding about the gene and the disease.
tumor (continued). "In addition, we analyzed MHC class I expression in cancer cells after stimulation with IFNγ and we found that all 7 ex vivo organoids cultures were formed by MHC class I proficient tumor cells." (PMID 31196138, 2019). "In contrast to the coculture with tumor cells, neither MΦ-polarizing stimuli such as 100 ng/mL LPS (lipopolysaccharide) + 100 U/mL interferon-γ (IFNγ), 20 ng/mL interleukin-4 (IL-4), nor the resolution-phase stimulus resolvin D1 increased miR-375 levels in MΦ." (PMID 30850595, 2019). "IFNγ, TNFα, and TGFβ1 are known to induce genotoxic stress, DDR signaling and senescence in both normal and tumor cells and we hypothesized that the JAK2V617F+ P-ECs are refractory to such treatment." (PMID 30967632, 2019). "When incubated with the BiTE in the presence of PD-L1+ tumor cells, PBMC from healthy human donors were activated as assessed by expression of the activation markers CD69 and CD25, their proliferation, and their production of IFNγ." (PMID 31001479, 2019). "The presence of intratumoral Tbet+ T cells suggests, but does not demonstrate, the presence of tumor-specific IFNγ-producing T cells that can stimulate the accumulation of CD8–Foxp3+Tbet+ Tregs." (PMID 30658697, 2019). "Likewise, respiratory hyperoxia in mice increased the ability of adoptively transferred T cells to curb primary tumor expansion and metastasis formation by augmenting their capacity to accumulate in the TME and produce IFNγ." (PMID 31244820, 2019). "To confirm anti-tumor specificity has been elicited, we measured IFNγ production of purified T cells in the presence or absence of tumor cells by Elispot assay." (PMID 31307539, 2019). "Increased CD8+ T cell effector function correlated with higher serum IFNγ levels, without related toxicities, and enhanced anti-tumor efficacy of the N-803 plus anti-PD-L1 combination versus either monotherapy." (PMID 30898149, 2019). "For both SV or SV plus α4-1BB treatment, the presence or absence of tumor did not significantly affect IFNγ levels, confirmeing that IFNγ production on day 7 was mainly an anti-viral response." (PMID 31307539, 2019). "Of note, PDL1 expression on Panc02 parental and Panc02-SIY tumor cell lines in vitro was minimal at baseline, but significantly increased 24h following radiation or stimulation with IFNγ, and was universally high by 72h (data not shown)." (PMID 30726287, 2019). "Tumor antigen-specific immunization with Ad.NYBR1 induced TAMs showing upregulated HLA-DR4 surface expression levels pointing towards a possible M1-like phenotype, likely due to the induction of an IFNγ-producing Th1 response." (PMID 31519152, 2019). "Cytokine production assay also showed that, compared with controls (vehicle or no treatment), SLR14 treatment promoted tumor-infiltrating CD8+ T lymphocytes to produce much higher levels of IFNγ and TNFα." (PMID 31601678, 2019). "NK-92 cells engineered with TGF-β/NKG2D CAR released a higher amount of IFNγ, showed a lytic capacity, inhibited Treg differentiation, exhibited an enhanced chemoattraction to TGF-b-releasing tumor cells, and inhibited tumor growth in a xenograft model of liver cancer." (PMID 31212634, 2019). "In this report, intra-tumoral injection with STING ligand resulted in elevated levels of TNFα, IL6 and CCL2, but no significant increase in IFNγ within the Panc02 tumor microenvironment." (PMID 31036082, 2019). "Both CD4+ and CD8+ T cells isolated 3 weeks post inoculation secreted less IFNγ than CD4+ and CD8+ T cells isolated 2 weeks after tumour inoculation, whether T cells were PD-1+ or PD-1-." (PMID 31277636, 2019). "Tumor samples from HPK1 KD mice demonstrated significantly upregulated key immune cell markers involved in mediating anti-tumor immunity, including CD4, CD8, IFNγ, TNFα, Granzyme B, CD28, CD11c and CD11b." (PMID 30913212, 2019).
tumor (continued). "It therefore remains unclear whether systemic priming of neutrophil progenitors by tumor-secreted factors, including G-CSF is a prerequisite for their differentiation into APC-like hybrid neutrophils upon exposure to IFNγ and GM-CSF at tumor site." (PMID 31616408, 2019). "Nevertheless, treatment with IFNα and IFNγ alone did not prevent disease and tumor formation in our studies." (PMID 31795203, 2019). "The remaining question not explained by this model is how IFNγ-producing cells are recruited into the tumor in the first place." (PMID 30873179, 2019). "In tumor, CD8+IFNγ+ cells were significantly increased in combination group only." (PMID 31320999, 2019). "Reactive T cells specifically recognized MLH1−/− tumor cells in IFNγ ELISpot, but lacked response towards NK cell targets YAC-1." (PMID 30630527, 2019). "These cytokines include interferon gamma (IFN-γ), which serves a critical role in tumor control, upregulating the immune response and exerting pro-inflammatory activity on immune infiltrates and tumor cells." (PMID 31861847, 2019). "Here, we offer an alternative but not mutually exclusive mechanism for enhanced host and anti-tumour immunity, underpinned by the capacity of T cells to generate more IFNγ relative to IL-10." (PMID 30700717, 2019). "PD-L1 expression in tumor is constitutively upregulated by oncogene alterations, such as PD-L1 and JAK2 genomic amplification or PI3K/AKT pathway activation, and is induced by the interferon gamma (IFN-γ) generated by infiltrating lymphocytes." (PMID 31443339, 2019). "In addition, high extracellular lactate levels (as encountered, for instance, in the tumor environment) were shown to result in intracellular acidification of CD8+ T cells and thus inhibition of NFAT2 induction, IFNγ expression, and anti-tumor immunity." (PMID 29568499, 2018). "Because basal levels of PD-L1 are almost undetectable in SKBR3 cells, and are unchanged following EGF or IFNγ treatment, we used mouse KPB6 tumor cells, which show a robust PD-L1 response to IFNγ, as an alternative model to confirm the PD-L1 surface expression phenotype." (PMID 30021161, 2018). "Furthermore, MGA012 enhances MGD007-mediated CTL activity and interferon gamma release upon exposure to gpA33-positive CRC and T cells, while MGD007 anti-tumor activity in preclinical mouse models is enhanced upon combination with anti-PD-1." (PMID 30400835, 2018). "Patients showing tumor response when treated with these agents display typically higher tumor-infiltrating lymphocyte counts (independent of baseline level) as well as upregulation of PD-L1 and IFNγ." (PMID 30514385, 2018). "In addition, an increase in tumor-infiltration of CD4+IFNγ+ T cells (p < 0.05) and CD8+ IFNγ+ T cells (p = 0.057) was detected in the H + anti-PD-1 combination therapy." (PMID 30333031, 2018). "Multiple Th1 cytokines and downstream targets were overexpressed in hot tumours (IFNG, CCL4, CCL5, CXCL9, CXCL10), along with costimulatory and coinhibitory receptors, suggesting these tumours were marked by a state of lymphocyte activation and counter-responses thereto." (PMID 30104673, 2018). "Additionally, NK cells can directly kill cancer cells, secrete IFNγ, TNF, GM-CSF, and other cytokines to promote CD8 T cell and APC activity, while also controlling tumor metastasis and recognizing CD8 T cell-resistant tumors with downregulated MHC I36." (PMID 29686284, 2018). "They showed that co-injection led to an increase in tumor growth and vascularization when the MSCs were induced with interferon-gamma (IFN-γ); whereas when the MSCs were not induced, the effect was much less." (PMID 29330447, 2018). "Loss of non-hematopoietic PD-L1 and inhibition of IFNγ signaling on peripheral LECs, thus preventing PD-L1 upregulation, improved the persistence of anti-tumor CD8+ T cell-mediated tumor killing and overall survival in melanoma-bearing mice." (PMID 30498499, 2018).
tumor (continued). "As per our previous report the IFNg potentially from T cell activation or other sources induces PD-L1 and IDO1 and potentially contribute to aggressive disease and worse outcomes in basal subtype tumours." (PMID 30308033, 2018). "We prepared lymphocytes from tumor-draining lymph nodes on Day 19, and analyzed the release of IFNγ when the lymphocytes were stimulated by co-culturing them with either FM3A tumor cells or with MBT-2 cells (negative control)." (PMID 30140379, 2018). "Splenic IL-8 was associated with weight and muscle loss and had a negative association with the same tumor proteins associated with increased TFBW (IL-4, Flt-3L, IFNγ, IL-7) and skeletal muscle weights (Flt-3L, IFNγ)." (PMID 30513792, 2018). "A recent study demonstrated that elevated levels of IFNγ arrested tumor blood flow without affecting tumor endothelial cell proliferation and apoptosis." (PMID 30373628, 2018). "Collectively, our data indicate that tumor-reactive T-cell populations should be enriched in the tumor (low DE50), that they are fully functional as effectors (high MFI of IFNγ venus signals) and that it is the expansion of these T-cells which makes the immunotherapy effective." (PMID 29348598, 2018). "In tumor lesions, CXCR3 expression might be sustained by the presence of pro-inflammatory molecules such as IFNγ that has been shown to sustain Tbx21 expression and subsequently TBET to positively regulate CXCR3 expression at the surface of T cells." (PMID 30420855, 2018). "In a first phase (elimination phase), the stimulated immune system produced many costimulating cytokines (TNFα, IL1, IFNα, TLR, ICAM1, IL2, IL12, IFNγ,) and less inhibitors (IL10, IL4, IL13, PD1/PD-L1, prostaglandins, LAG-3, TGFβ) resulting in efficient tumor cell killing." (PMID 29492219, 2018). "The expression of PD-L1 on tumors may be regulated by tumor intrinsic properties leading to its’ constitutive expression, but more commonly it is upregulated in response to TME mediated stimuli, usually interferon-gamma (IFN-γ) released by effector T cells." (PMID 29721192, 2018). "As a consequence, the immune cells seem not to be activated by the tumor cells and thus, no tumor infiltration and IFNγ release occurred." (PMID 29438316, 2018). "One of these putative tumor escape mechanisms is the expression of indoleamine 2,3-dioxygenase (IDO), which might be induced by IFNγ secretion by cytotoxic CD8+ T cells in the tumor microenvironment." (PMID 30050535, 2018). "Similarly, interferon-gamma (IFN-γ) releasing TH1 cells and natural killer (NK) cells have demonstrated anti-tumor potency." (PMID 30453514, 2018). "In contrast to the effect of TGFβ in combination with the K562 feeder cells, IL-2 plus TGFβ alone did not enhance the anti-tumor IFNγ and TNFα production, in agreement with what has been previously reported." (PMID 30400618, 2018). "Indeed, in colorectal cancer, TAMs are predominantly polarized toward a classically activated endotype and express pro-inflammatory cytokines such as IFNγ, which activate cytotoxic CD8+ T-cell responses to promote tumor destruction." (PMID 29594035, 2018). "In the present study, the IFNG-rs1861494 genotype was also combined with other genetic (i.e., MTHFR-rs1801131 genotype) and non-genetic factors (gender, primary tumor site, stage) to integrate a previously developed risk model for DFS." (PMID 30337874, 2018). "Following culture of these cells for 3 days with or without either a-CTLA4-TGFβRII or a-CTLA-4, tumor antigen-reactive T cells (CD3+/CFSElow/IFNγ+) were quantified by immunophenotype analyses." (PMID 29467463, 2018). "CD4+ T cells from TILs were significantly more demethylated in the IFNG locus compared to LN (p < 0.0001), whereas the methylation in LNs were higher compared to PBMC, suggesting an increased infiltration of Th1 IFN-γ producing CD4+ T cells into the tumour." (PMID 30075815, 2018).
tumor (continued). "Maximal tumour shrinkage coincided with a decreased Ki67 proliferative index, increases in tumour CD8+ cytotoxic T cells, FoxP3+ Tregs, and NK cells, as well as higher granzyme B staining and IFNγ production, confirming increased cytotoxicity." (PMID 30327563, 2018). "Since IFNγ exposure of cancer cells induces PD-L1 production, mutations in IFNγ signaling components JAK1 and JAK2 would lead to clonal evolution of PD-L1-negative tumor cells, which are not responsive to anti-PD-1 treatment." (PMID 30158932, 2018). "In addition to the significant increase in the number of CD8+ TILs, there is a significant increase in the expression of IFNγ and granzyme B in CD8+ cells in tumor tissues after being incubated with VentX-modified TAMs." (PMID 29872044, 2018). "The DE50 of the tumor was inversely correlated with the MFI of IFNγ venus signals of CD8+ T-cells, irrespective of the type of immunotherapy applied." (PMID 29348598, 2018). "In addition, NK cells can release pro-inflammatory cytokines and various chemotactic factors (IFNγ, TNFα, GM-CSF, CCL3/CCL4) potentially amplifying immune responses to the tumor." (PMID 30459756, 2018). "The tumor environment is likely to progress from an inflammatory surrounding with active T cells producing IFNγ, to a non-inflammatory environment populated by regulatory T cells and exhausted T cells that have stopped producing the cytokine." (PMID 30026743, 2018). "Additionally, inflammatory cytokines (Interferon gamma, CD3 and CD8) were focally increased in the tumor-sites in the immune responder group, suggesting specific immune responses against autologous tumor derived peptides bound to HSP-96." (PMID 29692957, 2018). "EGFR expression seems to be immunosuppressive and correlates with low PD-L1 expression (again potentially explained by low interferon-gamma level due to lack of tumor infiltrating lymphocytes)." (PMID 30577521, 2018). "Notably, neo-antigens increased with increasing expression of IFNγ and IL12RB2, indicating a Th1 skewed signature, as is desirable in an anti-tumor response." (PMID 29487705, 2018). "It would be, therefore, beneficial to be able to predict CD8+ T cell targets that are likely to be presented on tumor cells in both presence and absence of IFNγ." (PMID 30026743, 2018). "CD4+ T cells purified from fresh TUR-B tumour resections did not demonstrate any difference in methylation profile in the IFNG locus compared to PBMCs (p > 0.05)." (PMID 30075815, 2018). "Interferon-gamma production and upregulation of CD137 identified a core set of 6 neoantigens specifically recognized by patient’s autologous CD8+ T cells, 4/6 neoantigens were common between PDX and primary tumor." (PMID 30400835, 2018). "There may well be more total “non-invariant” diverse CD1d-restricted NKT cells in the body than iNKT and their ability to make Th2 cytokines appears to impair tumor immunity, whereas such NKT making IFNγ stratifies with cancer patient survival, as does iNKT." (PMID 29559971, 2018). "Finally, Nanostring analysis of RNA transcripts from tumor tissues revealed that ER+ tumors containing PD-1+ CD39+ CD8+ T cells had a significantly higher expression of gene signatures of inflammation and IFNγ signaling." (PMID 30400835, 2018). "Although initial IFNγ production is favorable for CTL activity, chronic exposure may lead to immunoediting in tumor cells." (PMID 30158932, 2018). "Consistent with the RNA-sequencing and RT-PCR results, Chi3l1 KO mice had increased mRNA for anti-tumor immunity molecules including CTSE, TRAL, IFNγ, T-bet, Perforin, and Granzyme B, while the expression of Th1-inhibitory molecules such as Twist1 and SOCS1 was significantly reduced." (PMID 29403003, 2018).
tumor (continued). "IFNγ and CCL4 are known to play critical roles in tumor progression." (PMID 28512255, 2017). "Numerous studies have demonstrated that RT leads to increased local production of soluble factors that promote anti-tumor immunity by enhancing activation of local innate immune cells and recruitment of tumor-reactive T cells (e.g., CXCL16, IL-1α/β, IFNγ, and TNFα)." (PMID 28134800, 2017). "To further examine whether galectin-3 retains IFNγ within the tumor microenvironment, we performed in vivo experiments using NSG mice bearing subcutaneous human tumor xenografts." (PMID 28986561, 2017). "PD-L1 is not expressed in most normal cells but can be induced in tumor cells by IFNγ in the tumor microenvironment." (PMID 28791250, 2017). "This process is downregulated in the tumour environment due to lack of IFNγ-induced STAT1 signalling." (PMID 28315228, 2017). "Negative factors that impact on both include tumour hypoxia, oxidative stress, tryptophan depletion due to high IFNγ-induced indoleamine 2,3-dioxygenase 1 (IDO1) levels and low pH." (PMID 29157300, 2017). "In contrast, MT/Shc2F/2F tumours are sensitized to IFNγ-driven immune surveillance in vitro, even though inhibition of pY239/240ShcA signalling does not upregulate IFNγ-stimulated activity in vitro." (PMID 28276425, 2017). "Modulation of PD-L1 levels occurs via two major pathways, the intracellular (innate) signaling pathway mediated by PI3K/AKT/mTOR activation and/or the extracellular induced (adaptive) pathway mediated by IFNγ production by TILs and subsequent IFNGRs/JAK/STAT signaling in tumor cells." (PMID 28107186, 2017). "However, in the presence of HER2(+) NCI-N87 tumor target, antitumor TH1 cytokines (TNFα and IFNγ) were released but only in the presence of BsAb, a format previously shown to induce immunologic synapse formation between the T cells and tumor targets." (PMID 28405494, 2017). "Simultaneously, we did not detect any significant increase in the expression of IFNγ mainly in the immunized groups of progressors, which would indicate involvement of NK cells in the tumor interactions." (PMID 28381295, 2017). "After pneumonectomy for isolated tumours, histologically normal human lung tissue far from the tumours contains both CD4 and CD8 cells with diverse T cell receptors (TCR) that express CD69, produce TNFα and IFNγ and proliferate in response to influenza virus." (PMID 28475122, 2017). "In para-tumor tissue of HBx model, the most significant different pathway is phagocytosis, while in DEN model the most significant different pathways are response to interferon-gamma and the negative regulation of neuron death." (PMID 29254483, 2017). "In line with this, DC loaded with whole tumor cell lysates and matured in the presence of IFNγ and three, but not two, TLR ligands were shown to convincingly activate tumor antigen-specific T cell responses." (PMID 28601925, 2017). "However, their increased efficacy in vivo was also found to be dependent upon secondary overexpression of CXCR3, the main receptor for the IFNγ-dependent chemokine ligands CXCL-9 and CXCL-10 found at elevated levels the TME of inflamed tumours." (PMID 29157300, 2017). "Unexpectedly and in contrast to IFNγ, type I IFNs were found in bone marrow transfer experiments to act on host hematopoietic cells and not on the tumor cell itself during the formation of a protective antitumor immune response." (PMID 28408907, 2017). "Activated PBMC produce IFNγ and are cytotoxic for multiple PDL1+ human tumor cells." (PMID 28938530, 2017). "The extrinsic induction is basically dependent on the pro-inflammatory cytokine interferon gamma (IFN-γ), which is secreted by CD8+ cytotoxic T cells; consequently, this induces the expression and transcription of PD-L1 on the surface of tumor cells and infiltrating immune cells." (PMID 28938605, 2017).